CAV1 (caveolin 1)
Diseases named in the same sentence as CAV1 in open-access papers (continued):
Sharing a sentence is not in itself a finding about the gene and the disease.
tumor (continued). "Conversely, in the tumor stroma (particularly in CAFs), autophagic degradation of Cav-1 promotes tumor growth and metastasis by providing nutrients and metabolic support." (PMID 41030451, 2025). "Among the different members of the caveolin family of proteins, Cav-1 has been extensively studied for its dual role in cancer biology, acting as either a tumor suppressor or promoter, contingent upon the tumor context." (PMID 40243482, 2025). "Our findings highlight a previously unrecognized role for CAV1-driven signalling in sustaining tumour dormancy, a critical and challenging therapeutic barrier underlying recurrence and pan-TKI resistance in HCC." (PMID 40715090, 2025). "An intrinsic membrane protein known as caveolin-1 (Cav-1) can take part in signal transduction and tumor progression, two processes that are related to the proliferation of tumor cells." (PMID 40579643, 2025). "The results of our present investigation suggest that CAV1 expression affects the tumor biological grade, particularly with respect to invasiveness." (PMID 40419438, 2025). "Among the caveolins, CAV1 is an important component of caveolae and has been shown to have two opposing roles in tumor progression." (PMID 40419438, 2025). "Mechanistically, the edited COPA (COPA^I164V) attenuates tumor growth by suppressing the PI3K/AKT/mTOR pathway via downregulation of Caveolin-1 (CAV1), thereby decreasing mTOR-driven cell proliferation and survival." (PMID 40852728, 2025). "Caveolin-1 is known to play a complex role in cancer, acting as both a tumor suppressor and promoter depending on the stage of cancer progression." (PMID 40963741, 2025). "Emerging evidence suggests that Cav-1 not only contributes structurally to caveolae formation, but also plays a dual role in cancer progression, acting as a tumor suppressor in certain malignancies while promoting oncogenic signaling in others." (PMID 40243482, 2025). "Specifically, LRP2 was significantly downregulated in RB compared to controls, whereas CUBN, DAB2IP, GIPC1, and CAV1 were significantly upregulated in tumor tissue." (PMID 41374987, 2025). "We did not perform in vitro or in vivo manipulations (overexpression, knockdown, or knockout) of LRP2, CUBN, CAV1, GIPC1, or DAB2IP to establish causality between expression changes and tumor phenotypes." (PMID 41374987, 2025). "Research has shown that CAV1 in the extracellular matrix is a potent biomarker for tumor progression and metastasis." (PMID 39763653, 2024). "Experiments suppressing Cav1 with siRNA counteracted enhanced NP delivery, supporting the involvement of a Cav1-induced transcellular route in tumor NP accumulation." (PMID 39193389, 2024). "Caveolin-1 (Cav-1) loss and an increase in MCT4 genes of neighboring fibroblasts that activate tumor-like metabolism in stromal fibroblasts." (PMID 38468988, 2024). "The top 25 keywords with the strongest citation bursts were presented, with caveolin 1 (13.13) ranking first, followed by tumor stroma (10.02)." (PMID 39876898, 2024). "Tumor microenvironment composition of high- and low-expressing CAV1 tumors was estimated using ECOTYPER." (PMID 38959243, 2024). "We compared the relative protein level of exosomal caveolin-1 between groups formed according to the values of prognostic parameters and according to tumor aggressiveness to analyze its potential as a prognostic biomarker." (PMID 38542507, 2024). "In this study, we investigated both gene and protein expression of CAV1 in TNBC in several large cohorts, focusing on potential associations between CAV1 and molecular features, tumor microenvironment composition, and clinical outcome." (PMID 38959243, 2024). "This ambiguity underscores the complex interplay between CAV1 expression, tumor characteristics, and the evolving TME." (PMID 39596307, 2024). "Caveolin-1 (CAV1) has been associated with PCa growth and its tumor promoter roles seem to be mediated by the interaction and consequent inhibition of PP1 activity." (PMID 39339236, 2024).
tumor (continued). "CAV1 functions as both a tumor promotor and a tumor suppressor, and this dual behavior of CAV1 often depends on downstream interacting partners." (PMID 38649663, 2024). "This study is, to our knowledge, the largest and most comprehensive to date investigating CAV1 in relation to molecular characteristics, tumor microenvironment composition, and prognosis in TNBC." (PMID 38959243, 2024). "Caveolin-1 (CAV1) is linked to chemoresistance and several important processes involved in tumor progression and metastasis, such as epithelial-mesenchymal transition (EMT)." (PMID 38959243, 2024). "Given that Ago2/CAV1 interaction is required for the dissemination of primary tumor cells in the lungs, we investigated the role of Ago2/CAV1 interaction in lung targeting of circulating cancer cells, the early stage of metastasis." (PMID 38649663, 2024). "High caveolin-1 expression is associated with shorter survival of GBM patients and enhanced tumor invasion." (PMID 39682716, 2024). "Both Ago2 and its associated miRNAs (e.g., miR-3613-3p) are actively sorted into cancer cell– or tumor-derived EVs in an Ago2/CAV1 interaction manner." (PMID 38649663, 2024). "Blocking Ago2/CAV1 interaction in cancer cells decreases the dissemination of primary tumor cells in the lungs." (PMID 38649663, 2024). "CAV1 expression was evaluated semi-quantitatively in tumor tissue from a homogeneous cohort of early-stage TNBC patients, detecting +cCAV1 and +sCAV1 in 10.3% and 42% of cases, respectively." (PMID 39596307, 2024). "The function of Cav-1 is highlighted in integrin-mediated ECM remodeling of tumor-associated fibroblasts, and in integrin-dependent invasion and metastasis of tumor cells." (PMID 39318372, 2024). "By knocking down CAV1, authors increased ROS and intracellular iron levels while reducing tumor cell growth in vitro." (PMID 38392321, 2024). "We took lung tissues from mice domesticated with sEVs with different CAV1 contents after planting tumor cells, and immunohistochemical staining was performed to detect the activation of Src/PI3K downstream of integrin α6β4 in the lungs of mice." (PMID 39494337, 2024). "Caveolin-1, while renowned for its diverse cellular functions including signal transduction, lipid homeostasis, and tumor suppression, plays an indispensable role in caveolin-mediated endocytosis." (PMID 39666389, 2024). "Further, caveolin-1 is overexpressed in PCa patients and correlates significantly with the aggressiveness of tumor forms." (PMID 38542507, 2024). "Accordingly, inhibition of CAV1 in mice reduced vascular density and tumor growth as well as in vitro inhibition of EphA2." (PMID 39596256, 2024). "CAV1 modulates key pathogenic processes involving the TME, including drug internalization, tumor-stroma interactions, hypoxia response, cellular metabolism, inflammation, and EMT15–17." (PMID 38509243, 2024). "All these suggest that CAV1 can regulate the assembly of cargoes on sEVs, simultaneously, and can be loaded on sEVs for translocation to distant organs to influence tumor progression." (PMID 39494337, 2024). "CAV1 influences tumor progression and chemotherapy response, particularly through its interaction with the tumor microenvironment (TME) and cancer metabolism." (PMID 39596307, 2024). "As Ago2/CAV1 interaction promotes mesenchymal and invasive phenotypes of cancer cells in culture, we investigated the role of Ago2/CAV1 interaction in tumor metastasis." (PMID 38649663, 2024). "CAV-1 exhibits high expression in a variety of malignant tumors and exerts a crucial influence on tumor metastasis." (PMID 38298655, 2024). "Complementing this, in vivo analyses demonstrated a marked reduction in lung metastatic foci in mice injected with Cav-1 knockout 4T1 cells as compared to wild-type cells, which was further corroborated by mRNA profiling of the primary tumor." (PMID 39244591, 2024).
tumor (continued). "We used sEVs inhibitor GW4869 to change CAV1 in BC-derived sEVs in situ tumor models and found that the number of recruited neutrophils was much higher in oeCAV1 sEVs group." (PMID 39494337, 2024). "For instance, CAV1 has been found to be expressed in various solid tumors, including cancerous cells and tumor stroma." (PMID 39286654, 2024). "The hyper-O-GlcNAcylation of Caveolin-1 (Cav-1) and c-Myc resulted in increased tumor cell motility, and enhanced cell migration and invasion." (PMID 38255793, 2024). "When Cav-1 was knocked down, the cytoplasm of cancer cells showed lower Cav-1 level and tumor tissues had a lower positive area of Cav-1." (PMID 39318372, 2024). "In essence, our study highlights that the prognostic impact of CAV1 in early TNBC patients is highly dependent on the tumor compartment where it expresses: the cytoplasm of tumor cells or tumor stroma." (PMID 39596307, 2024). "The evaluation of CAV1 protein expression was performed by immunohistochemistry according to different cellular compartments: cytoplasmatic expression in tumor cells or cCAV1, and expression in stromal cells or sCAV1." (PMID 39596307, 2024). "To elucidate the molecular mechanisms underlying the observed lung metastasis from the primary tumor in WT mice as compared to Cav-1 KO at weeks 2 and 3, as revealed by our IHC data, we conducted differential gene expression analysis in the primary tumor." (PMID 39244591, 2024). "CAV1 is a membrane protein involved in cell signaling, extracellular matrix organization, and tumor-stroma interactions." (PMID 38509243, 2024). "Caveolin-1 (Cav-1) is a critical lipid raft protein playing dual roles as both a tumor suppressor and promoter." (PMID 39244591, 2024). "Several studies show that CAV1 is also involved in the modulation of glycolytic activities (also known as the Warburg effect), which is key for tumor survival." (PMID 38959243, 2024). "Increased Ago2/CAV1 interaction with tumor progression promotes aggressive behaviors, including metastasis and EV miRNA release." (PMID 38649663, 2024). "It is known that CAV1 ensures the availability of the lipids required for maintaining the membrane integrity of tumor cells and modulates lipid metabolism and fatty acid oxidation." (PMID 38959243, 2024). "It is noteworthy that the prognostic value of CAV1 expression within the tumor epithelium and stroma remains a subject of contention." (PMID 39596307, 2024). "The interplay between CAV1 and the tumor microenvironment (TME) is crucial for understanding cancer metabolism." (PMID 39596307, 2024). "Caveolin-1 is a protein that stimulates the process of tumorigenesis but can also play a suppressive role depending on the type of tumor." (PMID 39684268, 2024). "Increased Ago2/CAV1 interaction with tumor progression promotes aggressive cancer behaviors, including metastasis." (PMID 38649663, 2024). "The role of Caveolin-1 in tumors is quite ambiguous; it can act both as a tumor suppressor and, conversely, promote tumor growth, depending on the tumor type and its stage of progression." (PMID 39598347, 2024). "Reduced expression in the primary tumor and interaction between Cav-1 and ITGα3 suggest a mechanism for metastatic enhancement." (PMID 39244591, 2024). "Blocking Ago2/CAV1 interaction attenuates the metastatic tumor formation of circulating cancer cells in the lungs and other organs." (PMID 38649663, 2024). "For instance, the interaction of EphA2 with Caveolin-1 (CAV1), an integral membrane protein, leads to the formation of new vessels in the tumor microenvironment of EWS cells." (PMID 39596256, 2024). "The expression of Cav-1 in tumor cells cultured on aligned fibers was upregulated, resulting in integrin β1 internalization and F-actin polymerization." (PMID 39318372, 2024). "Toll-like Receptor4 (TLR4) plays an essential role in the immune surveillance of tumor cells, and it has been shown that CAV1 is involved in the regulation of TLR431-33." (PMID 39494337, 2024).
tumor (continued). "For example, Silencing of CAV1 in fibroblasts results in increased tumour growth rate and chemoresistance in a human pancreatic cancer model." (PMID 38158643, 2024). "And this structural heterogeneity and orientation-driven promotion of tumor cell motility has also been demonstrated to be a Cav-1 indispensable process in vitro." (PMID 39318372, 2024). "Other TME factors such as hypoxia, neurotensin and tumor-derived exosomes containing Caveolin 1 (Cav-1) have been reported to be potent drivers of NE differentiation." (PMID 37761978, 2023). "It is possible that during cell transformation CAV1 expression drops and then increases in tumor progression, metastasis, and drug resistance." (PMID 36036057, 2023). "Cav-1 in CAFs has been found to have tumor-suppressive properties, and deletion of Cav-1 predicts poor prognosis." (PMID 37143134, 2023). "The opposite effect has been observed when E-cad is present; that is, E-cad cooperates with CAV1 to promote tumor suppression." (PMID 38069269, 2023). "It is possible that high expression of CAV1 is correlated with stromal changes directing toward more aggressive pro-tumor microenvironment." (PMID 36036057, 2023). "The eight genes (CAMK2N1, WNT7A, F2RL1, AREG, DEFB1, CNFN, TGFBI, and CAV1) included in the signature have been extensively studied and are known to be involved in tumor progression and EMT process." (PMID 37907576, 2023). "Here, it is important to note that CAV1 not only behaves as a tumor suppressor but also as a promoter of metastasis." (PMID 38069269, 2023). "At present, some researchers have found that Cav-1 can regulate the recruitment of mitochondrial dynamics-related proteins in tumor cells and regulate mitochondrial dynamics balance." (PMID 37234709, 2023). "E-cadherin is important in CAV1-dependent tumor suppression and prevents CAV1-enhanced lung metastasis." (PMID 38069269, 2023). "For example, downregulation of Cav1 in the early stages of tumorigenesis of certain cancer types promotes proliferation, angiogenesis, and tumor progression while in the later stages re-expression of the protein seems to support cell invasion and metastasis." (PMID 37998001, 2023). "The quantitative real-time PCR was performed to assess the expression of fibrosis-related genes (including E-cadherin, α-SMA, FAP, and Cav-1) in the fibroblasts of the tumor microenvironment." (PMID 38045487, 2023). "Here, we found that the targeting of P-selectin on tumour vasculature facilitates Cav1-dependent transendothelial transport and enhances drug delivery across an intact BBB." (PMID 36864161, 2023). "The first evidence highlighting the involvement of caveolin-1 in cell proliferation and tumor cell survival was first observed in Rous sarcoma virus (RSV)-transformed cells." (PMID 38067108, 2023). "According to “the autophagic tumor stroma model of cancer” malignant cells induce a down-regulation of caveolin-1 in CAFs leading to oxidative stress, autophagy, mitochondrial breakdown and a metabolic shift to aerobic glycolysis in these cells." (PMID 36831625, 2023). "Recently, with the remarkable development of cancer research, extensive findings have indicated that caveolin-1 is a key factor in the occurrence, progression and prognosis of tumor." (PMID 37576808, 2023). "The same behavior was observed for the abdominal tumor mass formed in the mice, where CAV1 promoted abdominal metastasis in A375 (CAV1) cells (0.475 ± 0.005 g), but E-cad partially decreased this behavior in A375 (E-cad) cells (0.286 ± 0.01 g)." (PMID 38069269, 2023). "Jun and CAV1 can regulate cell proliferation, apoptosis, and differentiation and inhibit tumor angiogenesis." (PMID 36835629, 2023). "Contrastingly, Cav1 is downregulated in oncogenically transformed cells, but then upregulated again in later tumor stages to potentially support tumor invasion and drug resistance, which has been demonstrated in prostate cancer." (PMID 37998001, 2023).
tumor (continued). "Overall, we demonstrated that CQ treatment was crucial to reduce the tumor burden and improve the survival rate in a xenograft mouse model with CAV1-positive SEM-type GC." (PMID 37919422, 2023). "With these subjacent mechanisms, the authors showed that stromal Cav1 can alter tumor microenvironments, facilitating tumor invasion in vivo." (PMID 36980283, 2023). "Most importantly, baicalein has anti-tumor effects on cancer cells, and it is able to inhibit the anti-apoptotic ability of Cav1." (PMID 37910338, 2023). "After one month, HE staining of the lung tissues revealed the presence of obvious cancer cells and tumor thrombi in the increased Cav-1 group, which proved the contribution of Cav-1 in the formation of BC lung metastasis." (PMID 37056561, 2023). "Targeting of tumour vasculature endothelial P-selectin promotes caveolin-1-mediated transcytosis for enhanced blood–brain barrier crossing of therapeutic nanoparticles against medulloblastoma." (PMID 36864161, 2023). "The formation of the first complex is associated with the ability of CAV1 to inhibit β-catenin/Tcf-Lef-dependent transcription of genes including survivin, COX-2, and cyclinD1 and therefore function as a tumor suppressor." (PMID 38069269, 2023). "Tumor-specific strong CAV1 in stromal cells and positive CAV1 in malignant cells were similar across CAV1 genotypes and haplotypes." (PMID 37017811, 2023). "In fact, our study showed a dramatic reduction in the plasmatic levels of exosomes expressing CD63 and of the surrogate tumor marker Caveolin-1 (cav-1) after ablative surgery." (PMID 38067397, 2023). "CAV1 genotypes and haplotypes in relation to clinical outcomes were assessed with Cox regression and adjusted for potential confounders (age, tumor characteristics, and adjuvant treatments)." (PMID 37017811, 2023). "An increasing number of studies have shown that the CAV family, especially CAV1 and CAV2, is significantly associated with tumor-associated processes." (PMID 36830672, 2023). "The role of Cav1 in cancer has also been widely studied, although the specific involvement of this protein as a tumor suppressor or oncogene seems to be context- and cell-dependent." (PMID 36980283, 2023). "For example, we know that Cav1 takes part in signaling cascades consistent with both tumor suppression and promotion, however, understanding how and when one set of characteristics is expressed over the other remains to be completely explained." (PMID 37998001, 2023). "It has previously been shown in caveolin (Cav)-1, Cav-2, and Cav-3; additionally, in Cav-1 and Cav-2, major structural proteins of caveolae infectious tumor metastasis." (PMID 37511762, 2023). "Ezrin also promotes communication between actin and caveolin-1-enriched tumor cell vacuoles, which form the driving structure of the cannibalistic process." (PMID 37511762, 2023). "The role of Cav1 in tumor growth, metastasis, and response to treatment appears to be most closely linked with its role in regulating apoptosis and cell death mechanisms." (PMID 37998001, 2023). "Prognostic survival time was measured, and the protein expression of Cav-1 in stromal cells and tumor cells was detected." (PMID 37828916, 2023). "These Cav1 null SHH-MB tumour mice showed latency and penetrance similar to those in Cav1 WT SHH-MB mice, with resultant tumours having similar histological features and levels of P-selectin expression." (PMID 36864161, 2023). "The xenografts result in nude mice further indicated that overexpression of CAV1 partially relieved the inhibition of tumor formation induced by knockdown of LINC01003 in vivo." (PMID 37270527, 2023). "Cav1 can act in accordance with tumor suppressor or promotor modalities depending on the cell type, tumor stage, and nature of the tumor stroma." (PMID 37998001, 2023).